DKK1 (dickkopf Wnt signaling pathway inhibitor 1)
Diseases named in the same sentence as DKK1 in open-access papers (continued):
Sharing a sentence is not in itself a finding about the gene and the disease.
osteoporosis (continued). "In postmenopausal females with osteoporosis and low bone mass (group I and II), a highly significant increase was found in serum levels of DKK-1 and in duration of postmenopause compared to controls (P < 0.001)." (PMID 23878759, 2013). "In further GWAS, both the studied CER1 and DKK1 variations should be included in order to evaluate their biological role in osteoporosis." (PMID 24138842, 2013). "The aim of this study was to assess serum level of Dickkopf-1 (DKK-1) in postmenopausal females and its correlation with bone mineral density (BMD) and serum biochemical markers in order to clarify if DKK1 has any role in the pathogenesis of osteoporosis." (PMID 23878759, 2013). "In conclusion, postmenopausal women with significantly increased serum DKK-1 had more significant osteoporosis in lumbar spine and femur neck as detected by DXA." (PMID 23878759, 2013). "Our results showed that DKK1 is increased in the serum of postmenopausal women with osteopenia and osteoporosis compared to controls (postmenopausal women with normal T score)." (PMID 23878759, 2013). "DKK1 overexpression is known for its pathological implications in osteoporosis, cancer, and neurodegeneration, suggesting the interaction with LRP5/6 as a potential therapeutic target." (PMID 27398238, 2012). "Studies demonstrate GC to be a very strong inducer of DKK-1 protein which leads to a decrease in osteoblast bone formation in GC induced osteoporosis." (PMID 22493705, 2012). "Preclinical studies with agents designed to block the functions of Sost and DKK1 have shown promise in treating bone disease and will likely be soon entering human clinical trials for the treatment of osteoporosis." (PMID 20948575, 2010). "Collectively, the roles of DKK1 in glucose metabolism and whether DKK1 inhibition yields a benefit on glycemic control in osteoporosis merits further investigation." (PMID 40149867, 2025). "Research indicates that knockout of Dkk1 and Sost can lead to increased bone mass, highlighting the potential therapeutic significance of targeting these genes in osteoporosis treatment." (PMID 39439909, 2024). "Moreover, patients with disuse osteoporosis due to long-term bed rest had elevated serum DKK1 level and reduced expression of β-catenin, resulting in decreased bone formation and increased bone resorption." (PMID 38744806, 2024). "Therefore, inhibiting the expression of Dkk-1 in bone tissue is an effective treatment for osteoporosis." (PMID 36979418, 2023). "Inhibiting the expression of SOST and Dkk-1 and activating the Wnt signaling pathway can effectively increase bone formation and inhibit bone resorption, which is considered an effective method to treat osteoporosis." (PMID 36979418, 2023). "This means that inhibition of osteogenesis accelerates the process of inflammatory osteoporosis and suggests that inhibition of Dkk-1 expression may help cure osteoporosis patients." (PMID 36979418, 2023). "Overall, while monoclonal antibodies to RANKL, Sclerostin, and DKK-1 for the treatment of osteoporosis are approved or in clinical trials, there is still a lack of knowledge regarding how to use these drugs effectively and which biomarkers must influence therapy selection." (PMID 37703870, 2023). "However, the balance between sclerostin and DKK-1 waned in GD patients with osteopenia or osteoporosis." (PMID 36506070, 2022). "The goal of this study was to assess the plasma level of sclerostin and DKK-1 in patients with GD and correlate it with the degree of bone involvement, including bone pain, bone marrow infiltration, Erlenmeyer (EM) flask deformity, and osteoporosis." (PMID 36506070, 2022). "Postmenopausal women with significantly increased serum DKK1 had more significant osteoporosis." (PMID 35634507, 2022).
osteoporosis (continued). "Regarding miR-335-5p, although basic research provides evidence that it promotes osteogenesis by targeting and downregulating DKK1, studies in osteoporosis-related bone disease correlate high levels of circulating miR-335-5p with osteoporotic bone disease with fractures." (PMID 34359778, 2021). "Moreover, patients with PLS3 osteoporosis have an increased expression of Dickkopf WNT signalling pathway inhibitor 1 (DKK1), an antagonist of the WNT-β-catenin signalling pathway, as well as an altered miRNA profile in serum." (PMID 33945105, 2021). "The role of DKK1 as a marker to predict osteoporosis and fracture risk cannot be confirmed due to a lack of consistent evidence." (PMID 32155909, 2020). "The proteins secreted by osteocytes, such as fibroblast growth factor-23 (FGF23), sclerostin (SOST), and dickkopf-1 (DKK1), could be candidates for osteoporosis screening and fracture prediction." (PMID 32155909, 2020). "A multicenter osteoporosis study conducted in five European countries reported a significant positive association between DKK1 and whole-body BMD in subjects, regardless of age and sex." (PMID 32155909, 2020). "Of note, DKK1 level is also increased in the brain from patients with Alzheimer’s disease, where senescent astrocytes accumulate, and also in patients with osteoporosis, where senescent bone cells are found." (PMID 31644429, 2019). "Therefore, Wnt-signaling inhibitors, such as sclerostin and DKK-1, are promising for osteoporosis treatment." (PMID 31137666, 2019). "Therefore, the use of bispecific antibodies against both sclerostin and DKK-1 is expected to promote new bone formation more than monotherapy with an anti-sclerostin antibody, even in patients with osteoporosis." (PMID 31137666, 2019). "We noted that DKK1 played important role in the development of osteoporosis." (PMID 28628652, 2017). "To explore whether DKK1-targeting miRNAs level was changed because of the pathogenesis of osteoporosis, we predicted miRNA targets through online software, and analyzed their correlation association." (PMID 28628652, 2017). "Dickkopf‐1 (Dkk‐1) and sclerostin, two extracellular negative regulators of the Wnt/β‐catenin pathway, are considered as potential targets for bone anabolic anti‐osteoporosis therapy." (PMID 26941261, 2016). "In addition, serum DKK-1 is increased in multiple myeloma (MM) patients with lytic bone lesions, menopause induced osteoporosis, Paget’s disease, glucocorticoid induced osteoporosis and estrogen deficiency." (PMID 26199898, 2015). "However, is also been described and inverse relationship between DKK1 and BMD, and higher DKK1 concentrations in patients with osteoporosis." (PMID 25369286, 2014). "Drugs with limited anti-tumor activity but which are anabolic for bone include intermittent parathyroid hormone and antibodies that neutralize the WNT inhibitors DKK1 and sclerostin, as well as the activin A blocker sotatercept and the osteoporosis drug strontium ranelate." (PMID 25757219, 2014). "This raises the issue that differences in serum DKK1 levels between the control and osteoporosis groups may be in fact an age-related phenomenon." (PMID 23878759, 2013). "It is now recognized that glucocorticoids also can activate DKK1 expression in OBs and may contribute to osteoporosis induced by chronic exposure to this class of drug." (PMID 24066119, 2013). "Furthermore, DKK-1 seems to induce the proliferation of human adult bone marrow stem cells and contribute to the control of osteoporosis, as mutations in LRP5 that impede binding of DKK-1 are responsible for high bone density." (PMID 21029453, 2010). "Therefore, targeting miR-203 and studying the mechanisms of DKK1 regulation could provide valuable insights into the mechanisms of osteoporosis." (PMID 39606935, 2025). "Therefore, inhibiting the expression of DKK1 in bone tissue may be an effective method for treating osteoporosis." (PMID 39606935, 2025).
osteoporosis (continued). "DKK1 may be another effective target for the treatment of osteoporosis." (PMID 39606935, 2025). "Therefore, we speculated that the H19‐miR‐29b‐3p‐DKK1 axis plays a crucial role in osteoporosis after SCI by regulating the differentiation of BMSCs." (PMID 38685675, 2024). "Since circulating DKK1 level was significantly correlated with the annual rate of change in cognition, DKK1 could be a novel biomarker and promising therapeutic target for osteoporosis in AD patients." (PMID 37635980, 2023). "Therefore, SOST and Dkk-1 have become very potent targets for the treatment of osteoporosis." (PMID 36979418, 2023). "Based on these findings, dual inhibition of sclerostin and DKK1 by administration of a bispecific antibody increased bone formation and improved fracture healing in rodents, suggesting that a simultaneous inhibition of sclerostin and DKK1 may result in superior results in osteoporosis treatment." (PMID 35160258, 2022). "Similarly, miR-203 showed regulatory effects on osteoblasts, but it could also further reverse the osteogenic differentiation in mesenchymal stem cells and participate in the pathogenesis of osteoporosis by binding to DKK1." (PMID 35355709, 2022). "Contrary to our primary hypothesis, we found that high levels of DKK-1 were associated with high total hip and lumbar spine BMD, and DKK-1 values were higher in patients without osteoporosis." (PMID 34497849, 2021). "Furthermore, Wnt inhibitor Dkk-1 seems to play a key role in osteoporosis." (PMID 31703281, 2019). "So, DKK-1 inhibition may have a therapeutic approach in osteoporosis." (PMID 23878759, 2013). "Specifically, inhibitors of the Wnt signaling pathway, including sclerostin, DKK1, WIF1, and SFRP, negatively regulate bone formation during osteoporosis." (PMID 39606935, 2025). "Sclerostin, an osteocyte-specific glycoprotein that inhibits the canonical Wnt pathway (similarly to DKK1 by binding to LRP5/6) is the target of romosozumab, the humanized monoclonal antibody treatment for osteoporosis." (PMID 40700291, 2025). "A previous study showed that DKK1 and SOST levels in the cortical bone matrix correlated positively with bone mass and strength in postmenopausal women with osteoporosis." (PMID 36768718, 2023). "Emerging osteoporosis therapies utilize novel mechanisms, including monoclonal antibodies against RANKL, DKK1, and sclerostin." (PMID 34065531, 2021). "The RA + osteoporosis group had elevated sRANKL levels (p = 0.005), higher sRANKL/OPG ratio (p = 0.017), decreased DKK-1 (p = 0.028), and lower SOST levels (p < 0.001)." (PMID 34497849, 2021). "In conclusion, for the first time we show functional evidence for the relevance of DKK1 in HBM phenotype and osteoporosis determination." (PMID 33354644, 2020). "For instance, dickkopf-1 (DKK1), a powerful antagonist of canonical WNT signaling pathway and biomarker for osteoporosis, was predicted as the shared targets of hsa-miR-133b, -20a-5p, -637, -214-3p, -106a-5p, and -135b-5p in our study." (PMID 33193074, 2020). "Our objective has been to study in detail the allelic architecture of three Wnt pathway genes: WNT16, DKK1 and SOST, in the context of osteoporosis." (PMID 30026596, 2018). "Dickkopf-1 (DKK1) is a powerful antagonist of canonical WNT signaling pathway, and is regarded as a biomarker for osteoporosis." (PMID 28628652, 2017). "Sclerostin and DKK1 can competitively bind to LRP5/6, a co-receptor in the Wnt signaling pathway, and inactivate it by regulating the transcription of downstream target genes, eventually inducing osteoporosis." (PMID 39606935, 2025). "Thus, targeting Wnt signaling pathway inhibitors, such as sclerostin, DKK1, WIF1, and SFRP, to regulate the expression of key molecules in the Wnt pathway represents a promising and safe therapeutic strategy for osteoporosis." (PMID 39606935, 2025).
osteoporosis (continued). "In contrast, Pitx1 overexpression induced osteoporosis by repressing Runx2, ALP, osterix, and OCN while increasing Wnt inhibitors (Sost, Dkk1); lithium chloride partly reversed this, showing how Wnt reactivation may counter senescence-driven bone loss." (PMID 41282593, 2025). "SOST and Dkk-1 can competitively bind to the co-receptor LRP5/6 in the Wnt signaling pathway and then regulate the transcription of downstream target genes, ultimately leading to the occurrence and development of osteoporosis." (PMID 36979418, 2023). "Therefore, sclerostin and DKK-1 neutralizing antibodies (romosozumab and BHQ880) are appealing new strategies for the treatment of inhibition of decreasing bone mineral density and osteoporosis." (PMID 36506070, 2022). "RA patients with osteoporosis had higher DKK-1 and SOST levels than RA patients without osteoporosis." (PMID 34497849, 2021). "Our main goal in this study was to determine if the interaction of sclerostin/Dkk1 coinhibition could be optimized to improve the osteoanabolic outcome over Scl‐mAb alone, which is an FDA‐approved strategy for the treatment of osteoporosis." (PMID 33977198, 2021). "In view of the specific role of osteocyte-related proteins such as DKK-1, SOST, and FGF23 in regulating bone health, it is tempting to speculate that their circulating levels could predict BMD, osteoporosis, and fracture." (PMID 32155909, 2020). "No reports have been made targeting sclerostin or DKK1 in osteoporosis in AD patients." (PMID 37635980, 2023). "We investigated whether DKK-1 and SOST serum levels are biomarkers of osteoporosis in RA patients." (PMID 34497849, 2021). "However, there have been no clinical trials of DKK-1 antagonist and the bispecific antibodies for osteoporosis treatment." (PMID 31137666, 2019). "Also higher DKK1 serum levels were established in postmenopausal women with osteoporosis without BC." (PMID 30227689, 2018). "Understanding of the molecular mechanisms involved in promoting bone density has been important to the development of multiple drug therapies for osteoporosis, such as the capthepsin K inhibitors Odanacatib and Balicatib, anti-SOST antibodies, anti-Dkk1 antibodies, and GSK3β and Sfrp1 inhibitors." (PMID 27483347, 2016). "Sclerostin and DKK1 have been shown to be differentially regulated by treatment agents used in osteoporosis with increases in sclerostin and either no change or decreases in DKK1 seen with antiresorptive agents such as bisphosphonates and denosumab, respectively." (PMID 25548714, 2014). "However, no study so far reported DKK1’s role in glucose homeostasis in patients with osteoporosis." (PMID 40149867, 2025). "Accordingly, inhibitors of this pathway, such as sclerostin, Dickkopf-1 (DKK1), WNT inhibitory factor 1 (WIF1), and secreted frizzled-related proteins (SFRPs), have a negative regulatory role in bone formation and may serve as effective therapeutic targets for osteoporosis." (PMID 39606935, 2025). "Instead, higher DKK-1 and SOST levels were identified in RA patients without osteoporosis patients, correlating with high total hip and lumbar spine BMD, as well as with a decreased of major and hip osteoporotic fracture assessed by FRAX." (PMID 34497849, 2021). "Moreover, at DXA, 33 (46.5%) ERA patients had osteopenia, and 16 (22.5%) had osteoporosis; patients with baseline bone erosions were more likely osteopenic/osteoporotic than non-erosive ones (p = 0.03), regardless of OPG, RANKL, and DKK1 plasma levels." (PMID 33732715, 2021). "Given that high plasma DKK1 levels in osteoporosis patients correlate negatively with BMD31, our observation that the plasma level of IL-32γ is correlated with BMD with advancing age supports a notion of the negative correlation between systemic IL-32γ and DKK1 for maintenance of bone mass." (PMID 28079119, 2017).
lung carcinoma (68 papers, 2007 to 2026). "Based on previous studies and our data, we postulate that overexpression of DKK1 can lead to transdifferentiation of lung cancer cells, resulting in the loss of their epithelial cell phenotypes and the occurrence of more mesenchymal cell phenotypes." (PMID 27240974, 2016). "DKK1 belongs to the Wnt signalling pathway associated with lung cancer metastasis." (PMID 35907982, 2022). "Considering the presence of DKK‐1 autoantibodies as a potential diagnostic biomarker in lung cancer 16, we hypothesized that the level of DKK‐1 autoantibodies is elevated in ESCC sera." (PMID 26988995, 2016). "This study clarifies that DKK1 mediates interactions between cancer cells and fibroblasts in gefitinib-resistant lung cancer, contributing to tumor progression." (PMID 40025612, 2025). "Hsa-miR-6807-3p has been identified to promote glioma tumorigenesis by regulating downstream DACH1 and it can also promote the development of lung cancer through the miR-6807-3p/DKK1 axis." (PMID 35578189, 2022). "DKK1 has been proved to be a new therapeutic target for lung cancer and esophageal cancer and plays an important role in the pathogenesis and development of gastric cancer, cervical cancer, and other malignant tumors." (PMID 36276284, 2022). "Conversely, following antibody-mediated blockade of Dkk-1 in metastatic lung cancer cells, microglia returned to their normal, more pro-inflammatory (non-suppressed) states." (PMID 35327593, 2022). "The overexpression of Dkk1 can facilitate apoptosis by suppressing cell proliferation and transformation, which occurs in multiple cancer cell lines, such as lung cancer, cervical cancer and liver cancer." (PMID 36430344, 2022). "The authors demonstrated a strong upregulation of DKK1 in various lung cancer and esophageal cancer cell lines." (PMID 34638464, 2021). "For instance, several studies showed a relationship between DKK-1 overexpression and worse prognosis in common tumors such as lung cancer (including non-small cell lung cancer) and rare malignancies such as chondrosarcoma." (PMID 34451907, 2021). "Tobacco smoking, as the main factor responsible for lung cancer, appears to activate Wnt signaling through polycomb-induced repression of the secreted Wnt antagonist Dkk1, resulting in a tumorigenic effect." (PMID 33585487, 2021). "This compound, the L-securinine, reduced the proliferation of lung cancer cells through DKK-1 inhibition." (PMID 34451907, 2021). "Subsequently, the metastatic lung cancer cells decrease Dkk-1 release removing the suppression on microglia that acquire a supportive phenotype." (PMID 34503141, 2021). "Here, we reported that lung cancer cell derived-exosomes controlled the activity of microglia in pre-metastatic niche by inducing the release of Dkk-1 from the BMECs." (PMID 33384994, 2020). "Here, we determined the role of Dickkopf-1 (Dkk-1) initially released from the BMECs after internalization of lung cancer cells exosomes, in the formation of metastatic niche in brain." (PMID 33384994, 2020). "Firstly, the IHC analysis displayed that there was a decline of Dkk-1 expression in the brain metastatic lesions compared to the primary lung cancer tissues." (PMID 33384994, 2020). "Further results showed that there was an obvious elevation of Dkk-1 in HBMECs compared to that of HUVEC under lung cancer cell-derived exosomes treatment, suggesting that the release of Dkk-1 in the progress displayed an organtropic pattern." (PMID 33384994, 2020). "The analysis of clinical data was also supported that the levels of Dkk-1 was negatively correlation with the occurrence of lung cancer metastasis to brain." (PMID 33384994, 2020). "The levels of Dkk-1 in HBMECs stimulated with lung cancer derived-exosomes from adenocarcinoma or SCLC were significantly higher than that of squamous cell carcinoma, which were in accordance with their potent to brain metastasis." (PMID 33384994, 2020).